MUC5B (mucin 5B, oligomeric mucus/gel-forming)
Diseases named in the same sentence as MUC5B in open-access papers (continued):
Sharing a sentence is not in itself a finding about the gene and the disease.
infection (continued). "Recently, however, two studies have reported RV-C15 – a prevalent strain in humans that may cause severe symptoms – infection of C57BL/6J mice induced the upregulation of remodeling-associated genes MUC5AC and MUC5B, elevated IL-25, IL-33, and TSLP levels, and increased numbers of lung ILC2s." (PMID 37773065, 2023). "It is tempting to speculate that the increased risk for infection with SARS-CoV-2 and the worse clinical outcome in black, Asian and minority ethnic populations in western societies may be associated with low carriage of the protective MUC5B T-allele." (PMID 34888316, 2021). "MUC5B is the predominant mucin in healthy human airways, and studies in mice deficient in Muc5b production have shown that Muc5b is essential for MCC and the maintenance of a healthy airway by controlling bacterial infection and resolving inflammation following infection." (PMID 30154090, 2018). "In addition the vMC0 infection stimulated increased pulmonary expression of MUC5B mRNA." (PMID 22355409, 2012). "Indeed, the polymorphisms within MUC5B and MUC7 genes may play a role in the susceptibility to infection (by viruses such as HIV)." (PMID 22929306, 2012). "Though normally produced at lower levels than MUC5B, which is the dominant mucin in healthy lungs, MUC5AC is induced upon infection, and high MUC5AC levels are protective against respiratory viruses." (PMID 40035770, 2025). "Although further research is needed, evidence suggests that MUC5B primarily forms long bundle-like strands, whereas MUC5AC appears as thin threads or sheets, typically upregulated during infections." (PMID 41158440, 2025). "Variants in other genes involved in IFN signaling and more recently in lung function (i.e., MUC5B and SFTPD) SNPs were found to be related to infection severity." (PMID 37515136, 2023). "To examine the pHAECs response to infection by the two viruses, we determined the mRNA levels for RSV M as well as those of IL-6, CX3CL1, CCL7 (MCP-3), Muc5AC, and Muc5B." (PMID 31330970, 2019). "When the cells were infected with HMPV, MUC5B was more induced in pediatric cells compared to adult cells on day 5 after infection, but no significant changes were observed in the expression of MUC5AC." (PMID 40143308, 2025). "Infection-related stimuli may elevate both mucins overall; however, within the RMPP mucus plug phenotype, the relative signal appears shifted toward MUC5B." (PMID 41561092, 2025). "MUC5B is thought to be constitutively produced and the dominant mucin by concentration, whereas MUC5AC is induced by external stresses such as irritants and infection." (PMID 36081767, 2022). "However, the constancy of the MUC5AC to MUC5B ratio during infection, coupled with the absolute increases in MUC5B, indicated that RV induced both MUC5AC and MUC5B expression." (PMID 35239513, 2022). "RV-C15 infection increased airway eosinophilic inflammation and mRNA expression of IL-13, Muc5ac and Muc5b in Rorafl/fl mice but not Rorafl/flIl7rCre littermates." (PMID 33968043, 2021). "MUC5B has an essential role in defense against bacterial pneumonia, and lack of this mucin severely affected infection-related survival in animal models." (PMID 30765827, 2019). "A non-statistically-significant increase in mRNA levels of Muc5b was observed in days 60 and 80 of infection." (PMID 31170201, 2019). "On the other hand, Muc5b was not induced after hMPV infection in WT mice, as similar expression was observed in mock-infected mice." (PMID 22606349, 2012). "However, we observed a higher level of Muc5B mRNA levels with r19FCX4C infected cells at day four post infection although the difference was not significant." (PMID 31330970, 2019). "No Ki67 and Muc5b immunoreactive cells were found in distal airways at any day of infection." (PMID 31170201, 2019). "In this work, we observed that only Muc5ac was induced after hMPV infection, but not Muc5b." (PMID 22606349, 2012).
infection (continued). "Unlike RV-A1, RV16 induced both, MUC5B and MUC5AC at 24 h post-infection and this was inhibited by ECSN6." (PMID 39538325, 2024). "The importance of MUC5B, and its role in mucociliary clearance (MCC), was demonstrated in studies of Muc5b knockout mice, where MUC5B, but not MUC5AC, was found to be indispensable for normal airway clearance and infection control in the airways." (PMID 36675209, 2023). "In contrast, our study did not observe any significant changes in muc5b expression levels in CEV-infected carp gills at both 6 and 11 days post-infection." (PMID 37465154, 2023). "We observed no significant increase in the ratios from baseline during infection in our experimentally infected individuals with COPD, suggesting a coordinated upregulation of both MUC5AC and MUC5B during RV infection in the individuals with COPD." (PMID 35239513, 2022). "Reduction of the CC10 protein in the whole lungs in the days 60 and 80 of infection, along with no changes in frequency of Clara cells in the distal airway suggest that CC10 and Muc5b were expressed in the same cell, i.e. Clara cell." (PMID 31170201, 2019). "The inhibitory activity of crude saliva and purified MUC5B and MUC7, from HIV negative (n=20) and HIV positive (n=20) donors, was tested by their incubation with subtype C HIV-1 and subsequent infection of peripheral blood mononuclear cells (PBMCs)." (PMID 22929306, 2012). "However, the differences in MUC5B and isoforms of MUC7 are not entirely explainable by the infection itself." (PMID 33224896, 2020). "In this study we have demonstrated that when the HIV-1 was incubated with the crude saliva and purified salivary MUC5B and MUC7 mucins and subsequently added to the CD4+ CEM SS cells no viral replication or infection of the CEM SS cells was detected by the p24 antigen assay." (PMID 17125499, 2006). "While gene expression of Muc5b and Muc5ac was no different between the two genotypes, at any age, we wondered if the epithelial layer of the CFTR-KO had more mucins in storage, prepared for release into the airway in the event of an infection or in response to an airway irritant." (PMID 35574458, 2022).
tumor (63 papers, 2004 to 2026). "Only the MUC5B gene expression was associated with tumor grades, which was higher in poorly differentiated tumors." (PMID 35572847, 2021). "Other markers for airway epithelial cells that are expressed through ALIw5 include the cell surface‐associated mucin MUC4, the gel‐forming mucin MUC5B, and the basal cell progenitor marker tumour protein p63 (TP63) (see GEO GSE136859, CompletePath_Counts.csv)." (PMID 32692488, 2020). "In normal goblet cells, AGR2 is required for folding and processing of secreted (MUC5AC) and membranous mucins (MUC1, MUC2, MUC5B;) which have also been implicated in various tumor-promoting processes." (PMID 29267283, 2017). "Moreover, many of these genes are associated with stemness, such as MUC5B, as well as tumor biology, including REG4, LYZ, EREG, KRT23, and RAMP1, which were also identified in a previous CRC single-cell study." (PMID 39350339, 2024). "Both MUC7 and MUC5B are members of the mucin family, overexpression and abnormal glycosylation of some transmembrane mucins in adenocarcinoma are associated with aggressive tumor proliferation and poor patient prognosis." (PMID 37726835, 2023). "In addition, in vivo xenografts of MUC5B-deficient cells resulted in a decrease in tumor growth when compared with xenografts of MUC5B-expressing mock cells." (PMID 36831639, 2023). "Previous studies have shown that MUC5B is closely associated with tumor metastasis." (PMID 37770976, 2023). "Interestingly, we observed that MUC5B is aberrantly expressed in tumor samples and that MUC5B high expression is associated with poorer survival." (PMID 33182511, 2020). "Another pathological analysis of NSCLC patients carrying EGFR mutations revealed that MUC5B expression levels in tumor tissues were strongly associated with patient overall survival, indicating that MUC5B may act as a novel prognostic biomarker in this subgroup." (PMID 41011152, 2025). "By promoting GINS complex expression and driving cell cycle progression and ferroptosis resistance, MUC5B contributes to aggressive tumor behavior." (PMID 41409294, 2025). "Given the DLBCL tumor-stimulating effects by inhibition of estrogen synthesis in xenograft experiments, it is likely that the suppressor function of NR4A and the pro-oncogenic activity of MUC5B contribute to a reduced tumor growth of ABC DLBCL." (PMID 36831639, 2023). "Heterogeneity expression of MUC5B and other mucins were associated with BRAF somatic mutation, tumor location and mismatch repair deficiency." (PMID 37726835, 2023). "A recent study showed the overexpression of MUC1, MUC19, MUC4, MUC5AC, and MUC5B in the mucinous metaplasia of tissues isolated from Pten conditional knockout mice and human PCa tumor tissues." (PMID 36980526, 2023). "IHC staining of tumor sections from PDAC patients showed that MUC5B and SERPINA1 are expressed by PDAC stromal cells (as well as by cancer cells)." (PMID 36316305, 2022). "The findings illustrated that the levels of MUC1 and MUC5B mRNA expression changed considerably across various tumour stages (P < 0.05)." (PMID 36059804, 2022). "Other signature genes (TP63, CERS3, CSTA, CLCA2, DSC3 and DSG3) upregulated in C1 tumours are also markers of the squamous-like subtype, while further columnar-like marker genes (MUC5B and RGL3) are upregulated in C2 tumours." (PMID 36207323, 2022). "Two secreted mucin mRNA (MUC5AC and MUC5B) were also increased in tumor samples (p < 0.01), whereas MUC6 was decreased in tumor samples compared to the normal pancreas." (PMID 33182511, 2020). "The expression of MUC5B was localized in the cytoplasm of tumor cells and was observed in 133 of 247 ACs and SCCs (53.8%)." (PMID 25733373, 2015).
tumor (continued). "In this study, although it was not statistically significant, there was a tendency for higher MUC5B expression in tumors with worse status for tumor size, nodal status, and pleural invasion." (PMID 25733373, 2015). "With multivariable analysis, MUC5B expression, tumor size, p-TNM stage, adjuvant chemotherapy, and vascular invasion were revealed to be significantly associated with survival." (PMID 25733373, 2015). "MUC5B expression identified by iTRAQ labeling was further validated using immunohistochemistry (IHC) on tumor tissue microarray (TMA)." (PMID 24176033, 2013). "In comparison to their study, we have also identified similar proteins in tumor tissues using iTRAQ labeling approach, such as eIF, collagen type VI, tenascin, anterior gradient protein, MUC5B, and hemoglobin subunit alpha BAL." (PMID 24176033, 2013). "Among early studies, mucin5B (MUC5B) has been suggested to play an important role in the tumor progression." (PMID 24176033, 2013). "We further analyzed the level of MUC5B in different stages of tumors and tumor-matched normal lung tissues using LC-MS/MS spectrum counts." (PMID 24176033, 2013). "Using a xenograft immunodeficient mouse model, we show that MUC5B promotes tumor growth and metastasis." (PMID 23056409, 2012). "MUC5B is positively correlated with cancer-associated fibroblasts and myeloid-derived suppressor cells in the tumor microenvironment (TME), indicating a role in TME-mediated tumor progression." (PMID 41409294, 2025). "Other research has suggested that overexpression of MUC5B could stimulate aggressive tumor cell behavior, increasing cell proliferation, tumor growth, and dissemination, highlighting the need for vaccine development." (PMID 41168812, 2025). "Given MUC5B’s tumor-specific expression and strong link to metastatic potential, targeted inhibition of MUC5B may offer a novel strategy for LUAD patients, especially those with advanced-stage disease." (PMID 41409294, 2025). "Additionally, single-cell RNA-seq analysis revealed that MUC5B is predominantly expressed in LUAD tumor cells, particularly in those with lymph node involvement, reinforcing its specificity as a therapeutic target." (PMID 41409294, 2025). "In addition to that, ECM‐related gene such as MMP9 and MUC5B were prominently upregulated in poorly group, indicating that the expression of these genes in macrophages plays a pivotal role in influencing tumour differentiation." (PMID 40847563, 2025). "We hypothesize that MUC5B may exert its pro-tumor effects in LUAD partly through upregulation of the GINS complex, linking it to genomic instability and ferroptosis resistance." (PMID 41409294, 2025). "NR4A2 and MUC5B protein expression in tumor cells was confirmed by IHC analysis of DLBCL samples." (PMID 36831639, 2023). "For example, MUC17, MUC5B and MUC6 gene mutations in tumor region T4A of PtA predict the perturbation of O-glycan biosynthesis and processing, and the GO terms in T4A differ from GO terms in other tumor regions." (PMID 26619400, 2015). "In our study, the detection of MUC5B in tumor tissue is particularly interesting." (PMID 24176033, 2013). "The predominant location of MUC5B in tumor cells was in the cytoplasmic membrane." (PMID 24176033, 2013). "Fifteen proteins, including MUC5B, showed significant changes in tumor tissues." (PMID 24176033, 2013). "In conclusion, MUC5B overexpression in MCF7 cancer cells may stimulate aggressive behavior of tumor cells by increasing cell proliferation, tumor growth, and dissemination." (PMID 23056409, 2012). "As a result, based on previous studies and this study, we hypothesized that MUC5B plays an important role in tumor metastasis, and exosome-based MUC5B would be significant in the incidence and progression of lung cancer as well as the catalyst for brain metastasis." (PMID 37770976, 2023). "This study suggests that MUC5B may represent a good target for slowing tumor growth and metastasis." (PMID 23056409, 2012).
tumor (continued). "Specifically, patients with tumours exhibiting high expression of ECM‐related (SPP1 and MUC5B) and complete active related genes (CFB and CCL20) in either the epithelial or macrophage compartment had significantly shorter disease‐free survival (DFS)." (PMID 40847563, 2025). "In specific, study reported that tumor cells showed expression levels of MUC1 (77%), MUC2 (2%), MUC5B (63%), MUC5AC (36%) and MUC6 (21%)." (PMID 40655139, 2025). "We identify the NR4A and MUC5B genes in ABC DLBCL being under estrogen control, with the tumor-suppressing NR4A gene family members being induced and the tumor-stimulating MUC5B being repressed." (PMID 36831639, 2023). "Cancerous squamous cell‐associated genes such KRT5, CDKN2A, and SERPINB3 were mainly enriched in the Stereo‐seq tumor areas, IGKC and IGLC2 were enriched in inflammatory areas, VIM in stromal areas, ADRA2A in blood vessels, and MUC5B in glands." (PMID 35986392, 2022). "In this investigation, the MUC5B mRNA expression level was almost twice as higher in LUAD compared to that in normal lungs and changed significantly across various tumour stages." (PMID 36059804, 2022). "To further examine the antitumor effect of tepotinib in high-MUC5B- and -c-MET-expressing GCs, we conducted an in vivo study using xenograft mice and found that tepotinib significantly inhibited tumor growth." (PMID 32825724, 2020). "Our in vitro and in vivo studies strongly supported the clinical evaluations of tepotinib, which prevented the EMT and tumor growth in c-MET- and MUC5B-expressing GCs." (PMID 32825724, 2020). "Conversely, the clear majority of the 10 most abundant human-derived gene products detected exclusively in tumor parenchyma (e.g., CEACAM5, MUC5B, FCGBP) were found to be involved in metastasis." (PMID 29899869, 2018). "From tumor immunophenotype analysis we interpreted that higher correlation of CDKN2 A and MUC5B to step 1, BIRC5 to step 2 while CCR9 to step 6 which means their up-regulation is associated with increased antigen recognition, antigen presentation and T cell activation." (PMID 40653567, 2025). "Furthermore, genes in our model such as MUC5B and TREM1 have been documented in relevant literature for their roles in the tumor immune microenvironment and prognosis, underscoring the model’s multidimensional novelty and clinical applicability." (PMID 40843359, 2025). "However, we also saw that some marker genes were preferentially detected in fresh versus FFPE transcriptomes, such as MUC5B and SFTPC in fresh or FFPE-derived tumor epithelial cells, respectively." (PMID 38300468, 2024). "While the RNA-seq data cannot distinguish between the tumor cell and stromal cell expression of MUC5B or NR4A, the use of highly human-specific primers when analyzing the expression of these genes in human U2932 tumor xenografts by RT-qPCR supports that the expression occurs in the tumor cells." (PMID 36831639, 2023). "Of note, the only patient with a diagnosis of small‐cell lung cancer and RNA data (Patient 4) had RNA profiles from two tumor sites that were similar to each other and distinct from the other NSCLC tumors with higher levels of several mucins and surfactant proteins (MUC4, MUC5B, MUC6, SFTPB)." (PMID 31747139, 2020). "Although it was not significant, there was a tendency toward higher MUC5B staining in the tumors with worse status for tumor size, nodal status, and pleural invasion." (PMID 25733373, 2015). "Our data demonstrated that the abundance of MUC5B in tumor tissue was significantly more than that in tumor-matched normal tissue regardless of tumor stages." (PMID 24176033, 2013). "The lack of MUC2, MUC5B, superficial MUC6 and sialylation of non-tumor samples confirms the pathologist's report stating that these specimens were normal." (PMID 22563496, 2012). "However, the role of exosomal MUC5B, SELL and APOH in tumor metastasis has not been reported, and the mechanism of their involvement in tumor metastasis remains to be further explored." (PMID 37770976, 2023).
tumor (continued). "Anti-MUC5B and anti-MUC6 antibodies did not stain PAC120 tumours (data not shown)." (PMID 14760390, 2004).